STAT3 (signal transducer and activator of transcription 3)
Diseases named in the same sentence as STAT3 in open-access papers (continued):
Sharing a sentence is not in itself a finding about the gene and the disease.
neurodegenerative disease (37 papers, 2014 to 2025). A disorder of the central nervous system characterized by gradual and progressive loss of neural tissue and neurologic function. "Surprisingly, E. cava decreased the activity of markers associated with inflammation (NF-kB and STAT3) and a neurodegenerative disease marker (glial fibrillary acidic protein, beta-amyloid) in the cerebrum and hippocampus of mice." (PMID 37111229, 2023). "STAT3 is associated with neurodegenerative diseases, wherein neuroinflammation increases the production of pro-inflammatory cytokines and the hyperactivation of microglia." (PMID 36138932, 2022). "Twenty-seven of these associations are known disease loci reported in GWAS, including APOE, MME, CD2AP, CD33 and IL34 for AD, and CD40, CD58, EVI5, IL7R and STAT3 for MS, and 23 associations represent previously unreported genetic associations with neurodegenerative diseases." (PMID 40037332, 2025). "The activity of Girdin and its signaling pathway-related proteins Akt and STAT3 decreased in neurons under high glucose stimulation, indicating that the mechanism of Girdin in brain degeneration caused by high glucose stimulation was closely related to the Akt and STAT3 pathways." (PMID 36329890, 2022). "Thus, spinal damage from injury or degenerative disease causes loss of motor neurons, astrogliosis and a significant increase in STAT3, which increases astrocyte activation." (PMID 24945434, 2014). "The Janus kinase/signal transducer and activator of transcription 3 (JAK/STAT3) pathway is responsible for the initiation of astrogliosis, and activation of this pathway is a hallmark feature of reactive astrocytes in many animal models of PD and other neurodegenerative diseases." (PMID 39183754, 2024). "On the other hand, Stathmin1 blockade, like Stat3 overexpression, has been discussed as a potential therapeutic issue to balance microtubule dynamics in neurodegenerative diseases." (PMID 39469187, 2024). "STAT3 is activated by aberrant Ca2+ signalling and has been reported as a key regulator of inflammation in neurodegenerative diseases." (PMID 34554282, 2022). "Age-related degeneration in the JAK2/STAT3 axis exerts crucial effect on the pathogenesis of neurodegenerative diseases." (PMID 33833662, 2021). "The signal transducer and activator of transcription 3 (STAT3), a major inducer of genes involved in apoptosis, cell growth, and inflammation, has been extensively implicated in neurodegenerative diseases." (PMID 34720873, 2021). "STAT3 is expressed in both hippocampal neurons and glial cells and is closely related to neurodegenerative diseases." (PMID 34471414, 2021). "STAT3 and NF-κB cross regulate and STAT3-induced NF-κB activation was shown to accelerate pathogenesis in neurodegenerative diseases." (PMID 32581761, 2020). "The Janus kinase/signal transducer and activator of transcription 3 (JAK/STAT3) pathway is a common mediator of astrocyte reactivity in neurodegenerative diseases (ND) and is highly conserved between disease states." (PMID 32973460, 2020). "RNA-seq analysis revealed a group of putative STAT3 targets that not only involves in the OXPHOS pathways, but is also implicated in neurodegenerative diseases." (PMID 32509786, 2020). "Crosstalk between STAT3 and NF-κB has been reported, and STAT3-mediated NF-κB activation plays an important role in the pathogenesis of neurodegenerative diseases." (PMID 32581761, 2020). "The JAK2/STAT3 pathway plays a protective role for neuroinflammatory and neurodegenerative diseases such as SAD." (PMID 32655767, 2020). "Compounds extracted from the leaves of V. amygdalina were evaluated for the immunomodulation of a series of transcription factors (NF-κB, STAT3 and Nrf2) involved in maintaining the chronic inflammatory condition of human degenerative diseases." (PMID 31830043, 2019). "Our study thus suggests a potential benefit of targeting the STAT3 pathway for neurotrauma or neurodegenerative diseases." (PMID 24945434, 2014).
neurodegenerative disease (continued). "Thus, the JAK2/STAT3 signaling pathway was targeted to evaluate its crucial role in immune and inflammatory responses, as its dysregulation is a key factor in various neurodegenerative diseases." (PMID 36648973, 2023). "It has been proposed that activation of STAT3 could be a consequence of neuroinflammation, and its modulation could enhance motor neuron differentiation and thus be beneficial in neurotrauma and neurodegenerative diseases." (PMID 35370543, 2022). "Selective inhibition of STAT3 pathway in astrocytes was found to suppress astrocyte activation or reverse their reactive phenotype, and improved the disease outcomes in several animal models of neurodegenerative diseases." (PMID 34057026, 2021). "Therefore, activation of STAT3 also plays an important role in nerve injury and neurodegenerative diseases." (PMID 34239694, 2021). "Thus, targeting the JAK2/STAT3 pathway can be used as a protective therapy for neuroinflammatory and neurodegenerative diseases like AD." (PMID 32655767, 2020). "JAK2/STAT3 activation, in particular, was illustrated to protect the neuron, while alteration of the same pathway might play a role in developing neurodegenerative diseases." (PMID 31996736, 2020). "STAT3 levels in microglia are enhanced in brain injury and a neurodegenerative disease model." (PMID 30309372, 2018). "In addition, STAT3 signaling is up-regulated in certain neurodegenerative diseases; for example, spinal cord microglia and reactive astrocytes have increased levels of phosphorylated STAT3." (PMID 27840601, 2016). "STAT3 signaling is also upregulated in certain neurodegenerative diseases." (PMID 24945434, 2014). "JAK2 and STAT3 are key members of the JAK/STAT pathway and play an important role in the pathophysiology of neurodegenerative diseases." (PMID 36627822, 2023). "STAT3 activation is not necessarily detrimental, and as has been shown in other models of CNS injury or neurodegenerative disease, the consequences are context-dependent." (PMID 37048051, 2023). "Recent literatures reported that resveratrol could inhibit oxidation and apoptosis in neurodegenerative diseases through the Nrf2/HO-1, SIRT1, RAX/P-PKR, and JAK2/STAT3/PI3K/AKT/mTOR signaling pathways." (PMID 36836502, 2023).
hematological cancers (29 papers, 2011 to 2025). "Activation status of both STAT5 and STAT3 might, therefore, provide important diagnostic and prognostic information in hematologic cancers." (PMID 31963765, 2020). "STAT3 is an oncogenic transcription factor that is hyperphosphorylated on its Y705 residue and transcriptionally activated in around 70% solid and hematological cancers." (PMID 36807142, 2023). "Signal transducer and activator of transcription 3 (STAT3), a member of the STAT family transcription factors, has functions similar to STAT5 and has been likewise linked to hematological cancers." (PMID 35494081, 2022). "While in normal cells the levels of STAT3 remain transient, in a high number of solid tumors and hematological cancers, STAT3 is constitutively active." (PMID 35890135, 2022). "For hematologic cancers in particular, targeting the overactivity of STAT3 with inhibitors has shown promise." (PMID 34671307, 2021). "Blocking this process seems to be an optimal solution to directly inhibit aberrant STAT3/5 signaling in hematopoietic cancers." (PMID 31963765, 2020). "STAT3/5 inhibitors are likely to become a valuable addition to the expanding arsenal of drugs against hematopoietic cancers and solid tumors." (PMID 31963765, 2020). "BCL2-family members, cell cycle-regulated genes, proto-oncogenes such as PIM1, c-MYC, BCL6, and genes involved in cytokine receptor signaling or immune response are often targets of STAT3/STAT5-mediated transcription in hematopoietic cancers." (PMID 31963765, 2020). "Most of the DBD inhibitors presented in this section were historically used against STAT3 and proved to be effective in some hematopoietic cancers." (PMID 31963765, 2020). "TERTp contains binding sites STAT3 and is overexpressed in prostate, breast, head, neck, and hematologic cancers, which implicates STAT3 as an important anticancer target." (PMID 33329574, 2020). "Due to an ever-growing list of STAT3/5 inhibitors and reviews in the field, we will focus on those that have been tested in hematopoietic cancers." (PMID 31963765, 2020). "The contribution of acetylation in the canonical functions of oncogenic STAT3/5 on one hand, and in hematopoietic cancers, on the other hand, remains very unclear." (PMID 31963765, 2020). "Most of these activities contribute to the known roles of STAT3/5 in hematopoiesis and hematopoietic neoplasms, and this knowledge complicates the already difficult task of targeting STAT3/5 for therapeutic purposes." (PMID 31963765, 2020). "Clinically, aberrant activation of STAT3 and, to some extent, STAT5, is associated with both solid and hematopoietic cancers." (PMID 31861720, 2019). "As a primary event during malignant transformation, somatic STAT3 and STAT5 driver mutations have been identified in hematopoietic neoplasms." (PMID 31861720, 2019). "Therapeutic approaches that exploit autophagy properties or target STAT3 represent a new field of investigation in hematological cancers." (PMID 31311917, 2019). "One of the downstream effectors of IL-8 is STAT3, which has emerged as a potential oncogene target in many solid and hematologic cancers, including MM." (PMID 25769101, 2015). "STAT3 was shown to be persistently activated in a variety of solid and hematological cancers and to promote metastasis." (PMID 24473086, 2014). "STAT3 is a transcription factor aberrantly activated in many human solid and hematological cancers and plays a role in oncogenesis." (PMID 21702955, 2011). "For instance, bortezomib and ruxolitinib (a JAK1/2 inhibitor targeting STAT3) have shown promise in other hematologic cancers and may enhance therapeutic strategies when combined with BCR inhibitors." (PMID 40129242, 2025). "Thus, the respective and specific functions of STAT3 and STAT5, as well as their interactions in hematopoietic cancers, still need to be refined to develop therapeutic strategies that selectively block STAT3 and/or STAT5 activity in these diseases." (PMID 31963765, 2020).
hematological cancers (continued). "This domain is involved in STAT3-mediated survival of solid tumor cells but its role in hematologic cancers is currently unknown." (PMID 31963765, 2020). "Persistent STAT3 activation had been described in various types of solid and hematological cancers." (PMID 29636641, 2018). "Signal transducer and activator of transcription 3 (STAT3) can be aberrantly activated in solid and hematological cancers including HCC and MM respectively." (PMID 34771643, 2021). "Collectively, these data would undoubtedly define STAT3 and STAT5A/5B as important therapeutic targets in hematologic cancers." (PMID 31963765, 2020). "Signal Transducer and Activator of Transcription (STAT) 3 and 5 are important effectors of cellular transformation, and aberrant STAT3 and STAT5 signaling have been demonstrated in hematopoietic cancers." (PMID 31963765, 2020). "STAT3 and the two closely related STAT5A and STAT5B proteins are key players in the development of solid and haematopoietic cancers." (PMID 32667731, 2020). "This review summarizes the current knowledge of oncogenic STAT3 and STAT5 functions in hematopoietic cancers as well as advances in preclinical and clinical development of pharmacological inhibitors." (PMID 31963765, 2020). "Modalities for targeting STAT3 and STAT5 in hematologic cancers can be classified into direct and indirect approaches." (PMID 31963765, 2020). "In this review, we discuss the functions and the roles of unphosphorylated STAT3/5 in the context of chromatin remodeling, as well as the impact of STAT5 oligomerization on differential gene expression in hematopoietic neoplasms." (PMID 31817042, 2019). "In this review, we will first summarize the respective contribution of STAT3 and STAT5 in hematologic cancers as well as the canonical and non-canonical oncogenic properties of STAT3/STAT5." (PMID 31963765, 2020). "Finally, we will describe the different strategies used to target STAT3 or STAT5 and will discuss the potential future development of single or combined therapies to block STAT3 and/or STAT5A/5B activity/expression in hematologic cancers." (PMID 31963765, 2020). "The methylation status of STAT3 and STAT5 in hematopoietic cancers has yet to be investigated." (PMID 31963765, 2020). "Direct inhibitors of STAT3 and STAT5 that have been tested in hematologic cancers." (PMID 31963765, 2020). "Indirect inhibitors of STAT3 and STAT5 that have been tested in hematologic cancers." (PMID 31963765, 2020).
blood cancers (25 papers, 2013 to 2026). "All these studies support the association between STAT3 and resistance to apoptosis, and confirm an important role for Birc5 in hematological neoplasms and solid cancers." (PMID 33557010, 2021). "We observed that STING was positively correlated with IFN-γ and IL6/JAK/STAT3 signaling in most blood cancers." (PMID 39975558, 2025). "Mechanistic analyses have demonstrated that OPB-111077 significantly inhibits the STAT3 activation pathway, with antitumor effects against a wide range of human solid and blood tumor cell lines." (PMID 38938528, 2022). "The role of other miRNAs and of long non-coding RNAs such as miR-30 and CASC2, which can regulate STAT3 signaling in solid malignancies, needs to be further elucidated in the context of hematological neoplasms." (PMID 31684088, 2019). "STAT3 is a particularly attractive therapeutic target because it is constitutively active in most human solid and hematological tumors, and at the same time only transiently active in normal tissues." (PMID 31684088, 2019). "Aspartic acid at position 661 (D661) is the most frequently mutated residue in the STAT3 SH2 domain, with 156 cases reported in the COSMIC database and the STAT3D661Y and STAT3D661V variants consistently associated with blood cancers in the gnomAD and COSMIC databases." (PMID 41527523, 2026). "Nevertheless, the most likely molecule compensating for STAT5 is STAT3, and thus, dual STAT3/5 degradation could be more effective to fight blood cancers." (PMID 38618957, 2024). "In blood cancers, however, STAT1, STAT3 and STAT5 play a dominant role and single STAT‐targeting therapies may suffice, also reflecting their less complex genetic driver mutation landscape." (PMID 35229974, 2022). "Nevertheless, for tumors that do not express these chemokines or blood cancers, STAT3 activation in T cells might provide a persistence advantage with no reduction in trafficking." (PMID 35270020, 2022).
neurological disorders (25 papers, 2017 to 2026). "The involvement of the JAK2/STAT3/Fyn/NMDA signaling pathway in these effects highlights DBZ as a potential candidate for treating neurological disorders associated with neuroinflammation." (PMID 40349773, 2025). "While abnormal expressions of miR-124 and STAT3 have been implicated in various nervous system diseases, the inhibition of oxidative stress and apoptosis by miR-124 targeting STAT3 in HIBD has not been reported." (PMID 38319722, 2024). "The potential involvement of NF-κB and STAT3 was investigated because the promoters of both TNFα and IL-6 contain binding sites for NF-κB and STAT3, which are known to be involved in neurological disorders associated with increased inflammation." (PMID 29228978, 2017). "Other identified regulators are involved in reactive gliosis, such as SOX2 which plays a role in astrocyte activation after traumatic brain injury, and STAT3 which has been widely implicated in astrocyte activation and inflammation during neurological disease, and under hypoxic/ischemic conditions." (PMID 38528608, 2024). "For some somatic variants, it may even be possible to target the affected pathway itself, as examples such as BRAF or STAT3 inhibitors for other autoimmune and neurological diseases illustrate." (PMID 30541027, 2019). "They attenuate inflammation-induced disorders such as cardiovascular and neurological disorders via down-regulating pro-inflammatory cytokines (IL-6, CRP, COX-2, LPO, TGF-β1, NF-κB, and TNF-α), and pathways (IRAK4, MAPK, JAK/STAT3, TLR4, and ERK)." (PMID 41640995, 2026). "PHBs can prevent apoptosis, inflammation, mitochondrial dysfunction, and autophagy in neurological disorders through different molecules and pathways, such as OPA-1, PINK1/Parkin, IL6/STAT3, Tau, NO, LC3, and TDP43." (PMID 35847581, 2022). "Amongst the substantial TFs associated with the DEGs were early growth response 1 (EGR1), signal transducer and activator of transcription 3 (STAT3) and peroxisome proliferator activated receptor gamma (PPARG), which are involved in different neurological diseases." (PMID 32967368, 2020). "Additionally, STAT3 and STAT5 were two fundamental signaling pathways governing inflammatory response in various neurological diseases." (PMID 28293439, 2017).
head and neck tumor (19 papers, 2013 to 2025). "In this study, the STAT3 ODN-decoy was injected intratumorally to measure the inhibition of STAT3 target gene expression, STAT3 activation level, and apoptosis in head and neck tumors." (PMID 38067351, 2023). "It has been confirmed that IL-6 is involved in the epithelial to mesenchymal transition in head and neck tumor cells via the activation of the STAT3/SNAIL signaling pathway, and STAT3 knock down significantly reverses IL-6-mediated EMT changes." (PMID 34943943, 2021). "Signal transduction and activator of transcription 3 (STAT3) is highly phosphorylated in almost all head and neck tumours." (PMID 32869923, 2020). "The STAT3 signaling also mediates IL-6 induced EMT (epithelial-mesenchymal transition) to promote the metastasis of head and neck tumor cells." (PMID 27012679, 2016). "It has also been reported that the activation of Stat3 induced EMT through Snail activation in head and neck tumor." (PMID 25879771, 2015). "Recently, a phase 0 clinical trial evaluating a STAT3 decoy oligonucleotide demonstrated decreased expression of STAT3 target genes in head and neck tumors following intratumoral injection." (PMID 26272737, 2015). "Several small molecules targeting Stat3 are currently being evaluated for head and neck tumors in Phase I/II clinical trials (clinicaltrials.gov), including WP1066." (PMID 24167583, 2013). "STAT3 shRNA can reduce specific and sustained EGFR-dependent activation of STAT3 in the HN5 head and neck tumor cell line." (PMID 38067351, 2023). "It was shown in a recent study that resveratrol could radiosensitize and block the STAT3 signaling pathway by inducing SOCS-1, thereby reducing STAT3 phosphorylation and proliferation in head and neck tumor cells." (PMID 29194365, 2017).